GSDMD (gasdermin D)
Diseases named in the same sentence as GSDMD in open-access papers (continued):
Sharing a sentence is not in itself a finding about the gene and the disease.
kidney damage (6 papers, 2021 to 2025). "As GSDMD, a critical pyroptosis player, and inflammation play an important role in causing kidney damage and dysfunction, the potent inhibition of pyroptosis and inflammation by lithium may explain, at least in part, its protective effects on kidney function in this study." (PMID 40095208, 2025). "We found that the Caspase-11/GSDMD signaling were markedly activated in the kidneys of hyperuricemic nephropathy." (PMID 38436813, 2024). "Collectively, these data provide robust support for the hypothesis that GSDMD/Caspase-11 contributes to the release of NETs from neutrophils in hyperuricemic nephropathy." (PMID 38436813, 2024). "To investigate whether pyroptosis is involved in TCE-induced kidney damage, we tested the two main executive molecules, GSDMD and GSDME." (PMID 35656289, 2022). "Moreover, aligning with the prior study, our study noted an elevation in GSDMD within the peritubular compartment following adenine treatment, with no discernible increase in proximal tubular cells, suggesting GSDMD in inflammatory cells were involved in hyperuricemic nephropathy." (PMID 38436813, 2024). "To address the question of whether Caspase-11/GSDMD played a vital role in NETs generation in hyperuricemic nephropathy, we accessed the expression of myeloperoxidase (MPO) and histone H3 (H3) in the kidney tissue from Gsdmd−/− mice, Caspase-11−/− mice, and WT control mice." (PMID 38436813, 2024).
lupus nephritis (6 papers, 2021 to 2024). Glomerulonephritis in the context of systemic lupus erythematosus. "We found GSDMD is highly expressed in myeloid cell but exert a protective effect in the development of lupus nephritis." (PMID 38831451, 2024). "Multiplex immunohistochemistry (mIHC) revealed that renal biopsy samples from lupus nephritis (LN) patients showed heightened expression of GSDMD in the glomeruli, using renal peritumoral tissue from renal tumor patients as controls." (PMID 38881675, 2024). "Immunofluorescence of renal biopsy samples from lupus nephritis (LN) patients showed increased neutrophil infiltration in the glomeruli and tubulointerstitial, wherein these neutrophils exhibited higher levels of GSDMD expression as compared to the resident renal cells." (PMID 36797275, 2023). "Another study showed that Ac-FLTD-CMK reduced GSDMD protein expression and production of cytokines in a murine model of lupus nephritis, thus reducing glomerulosclerosis and immune cell infiltration and preventing the development of lupus nephritis." (PMID 37275856, 2023). "However, quercetin reversed the expression of NLRP3, ASC, caspase-1, N-GSDMD, and IL-1β induced by IL-33, indicating that quercetin can relieve inflammasome- and GSDMD-mediated pyroptosis in the cellular model of lupus nephritis." (PMID 36421424, 2022).
neuroblastoma (6 papers, 2021 to 2026). Neuroblastoma (NB) is the most common solid, extracranial childhood tumor. "The same molecular pathway that must be inhibited to treat neuropathic pain (e.g., NLRP3/caspase‐1/GSDMD) is the one that should be selectively induced to treat neuroblastoma." (PMID 41574659, 2026). "This context‐dependent duality presents a fundamental therapeutic challenge: the same molecular pathway (e.g., NLRP3/caspase‐1/GSDMD) that must be inhibited to treat neuropathic pain is the one that should be strategically induced to treat neuroblastoma, necessitating a precision medicine approach." (PMID 41574659, 2026). "Thus, the authors concluded that BPA could induce pyroptosis in neuroblastoma cells through the NLRP3/caspase-1/GSDMD pathway, mediated by ER." (PMID 37855918, 2024). "We measured the mRNA levels of the gasdermin family genes (GSDMA, GSDMB, GSDMC, GSDMD and GSDME) in all five wild-type NB cell lines to understand the genes activated in neuroblastoma." (PMID 38893185, 2024). "In SH-SY5Y neuroblastoma cells, the depletion of PINK1, ATP13A2, and/or GBA resulted in cell death, as demonstrated by elevated LDH levels, decreased cell viability, and increased levels of the cleaved form of caspase-3 or Gasdermin D." (PMID 34035300, 2021). "However, human neuroblastoma SH‐SY5Y cells did not express GSDMD, and infection did not induce phosphorylation of MLKL, a necroptosis marker, in SH‐SY5Y cells." (PMID 37646198, 2023). "The human neuroblastoma cell line SH‐SY5Y used in this study did not express CASP1 and GSDMD, thus excluding canonical inflammatory pyroptosis." (PMID 37646198, 2023).
Parkinson disease (6 papers, 2021 to 2026). A progressive degenerative disorder of the central nervous system characterized by loss of dopamine producing neurons in the substantia nigra and the presence of Lewy bodies in the substantia nigra and locus coeruleus. "For instance, in models of Alzheimer's and Parkinson's diseases, pathological proteins such as β-amyloid and α-synuclein can activate inflammasomes and trigger the caspase-1/GSDMD pathway, ultimately resulting in neuronal death." (PMID 41563626, 2026). "BA results in the remission of neuroinflammation through limiting the NLRP3/caspase-1/GSDMD pathway in mice with Parkinson's disease." (PMID 39662962, 2024). "In a TLR4-dependent manner, MPTP activated NLRP3/caspase-1/GSDMD cascade in mouse model of Parkinson’s disease." (PMID 39253076, 2024). "NLRP3/caspase-1/GSDMD pathway was shown to contribute to neuroinflammation in mouse model of Parkinson’s disease induced by N-methyl-4-phenyl-1,2,3,6-tetrahydropyridine (MPTP)." (PMID 39253076, 2024). "The ability of BHB to suppress pyroptosis via inhibiting the STAT3/NLRP3/GSDMD axis was previously documented in Parkinson’s disease models." (PMID 37841914, 2023).
pulmonary fibrosis (6 papers, 2022 to 2025). Chronic progressive interstitial lung disorder characterized by the replacement of the lung tissue by connective tissue, leading to progressive dyspnea, respiratory failure, or right heart failure. "This study confirmed that LPS-induced pulmonary fibrosis is associated with pyroptosis and that LPS can promote the expression of the pyroptosis-related factors Caspase1, Gasdermin D and IL-1β." (PMID 38875245, 2024). "Recently, it was observed that GSDMD-/- mice, deficient for pyroptosis, had down-regulated levels of proinflammatory cytokines IL-1β/IL-6 and less lung fibrosis, supporting the crucial role of GSDMD and pyroptotic ICD in pulmonary inflammation." (PMID 35846433, 2022). "Given that GSDMD controls the release of IL-1β downstream of multiple inflammasomes, GSDMD is an attractive target for pulmonary fibrosis." (PMID 36865908, 2023). "Inhibition of NLRP3/Caspase-1/GSDMD-mediated pyroptosis largely reversed the injurious effects of hyperoxia, resulting in attenuated lung inflammation, improved alveolarization and pulmonary vascular development, and alleviated pulmonary fibrosis." (PMID 40486518, 2025).
Rotavirus infection (6 papers, 2017 to 2025). Infection with any of the rotaviruses. "Moreover, GSDMD-deficient mice are more vulnerable to rotavirus infection, suggesting that rotavirus clearance requires GSDMD." (PMID 38177104, 2024). "For example, GSDMD-deficient mice are more susceptible to rotavirus infection than wild-type mice." (PMID 35677444, 2022). "GSDMD knockout in the intestine in vivo significantly enhances the susceptibility of mice to rotavirus infection, indicating a protective role of GSDMD against rotavirus infection." (PMID 34899666, 2021). "Furthermore, mice deficient in either GsdmD or NLRP9b displayed increased susceptibility to rotavirus infection in vivo." (PMID 28979266, 2017). "In intestinal epithelial cells, NLRP9b is involved in GSDMD-induced pyroptosis to restrict rotavirus infection." (PMID 35677444, 2022). "These all indicate that GSDMD undermines coronavirus replication, consistent with rotavirus results in which GSDMD knockout potently enhances rotavirus infection." (PMID 34899666, 2021). "Furthermore, DHX9 pairs with Nlrp9b to sense short dsRNA, forming inflammasome complexes that promote the maturation of interleukin-18 and GSDMD-induced pyroptosis, thus providing resistance against rotavirus infection in IECs18." (PMID 38594251, 2024). "As a critical mechanism of host defense, GSDMD activation–mediated IL-18 release contributes to the killing and clearance of gastrointestinal pathogens in intestinal cells and immune cells, which drives anti-rotavirus immunity and protects mice against rotavirus infection." (PMID 39927458, 2025). "A very recent study using a mouse model of rotavirus infection reported that activation of a novel NLR inflammasome that recognizes viral dsRNA, NLRP9b, contributed to the restriction of rotavirus replication in IEC organoids, at least partly through gasdermin D-induced pyroptosis." (PMID 28979266, 2017).
abdominal aortic aneurysm (5 papers, 2023 to 2024). Enlargement and ballooning of the vessel that supplies arterial blood to the abdomen, pelvis and legs. "GSDMD deficiency in VSMCs ameliorates vascular remodeling in abdominal aortic aneurysm." (PMID 38463394, 2024).
acute liver failure (5 papers, 2022 to 2026). Rapid deterioration of liver function causing encephalopathy and coagulopathy. "It has been reported that nucleotide‐binding and oligomerization domain‐like receptor (NLR) family pyrin domain containing 3(NLRP3), caspase‐1, and gasdermin D (GSDMD) are activated in D‐galactosamine/lipopolysaccharide (D‐gal/LPS)‐induced acute liver failure." (PMID 35184410, 2022). "In contradiction, others demonstrated an essential role of GSDMD-mediated hepatocyte pyroptosis in acute liver failure." (PMID 35972273, 2022).
acute myeloid leukemia (5 papers, 2021 to 2024). Acute myeloid leukemia (AML) is a group of neoplasms arising from precursor cells committed to the myeloid cell-line differentiation. "Activation of the Caspase1/GSDMD pathway by Val‐boroPro leads to pyroptosis in acute myeloid leukaemia." (PMID 38804602, 2024). "Serine dipeptidase DPP8/9 inhibitors, which activate GSDMD-mediated pyroptosis in human myeloid cells, induce pyroptosis in most human acute myeloid leukemia cell lines and primary cells but not cells from other lineages, presenting a novel therapeutic strategy for acute myeloid leukemia." (PMID 36742298, 2023). "On-going clinical trials investigating the role of gasdermins in cancer are currently undergoing, including the analysis of GSDMD cleavage in cutaneous T-cell lymphoma (NCT05333367), and another is investigating GSDMD and inflammasome activation in acute myeloid leukemia patients (NCT06200441)." (PMID 38645692, 2024).
endothelial dysfunction (5 papers, 2023 to 2025). In vascular diseases, endothelial dysfunction is a systemic pathological state of the endothelium (the inner lining of blood vessels) and can be broadly defined as an imbalance between vasodilating and vasoconstricting substances produced by (or acting on) the endothelium. "Caspase-4/11-mediated GSDMD cleavage has been reported to contribute to pyroptosis, endothelial dysfunction, and subsequent pulmonary arterial hypertension." (PMID 39253076, 2024). "Dysfunction of endothelial cells initiates atherogenesis, where GSDMD-mediated pyroptosis promotes endothelial dysfunction." (PMID 39253076, 2024). "The results of this study indicate that Sil can decrease the expression of IL-18, NLRP3, caspase-1, and GSDMD and increase the expression of eNOS to inhibit inflammatory reaction and improve endothelial dysfunction." (PMID 37636019, 2023). "Furthermore, the miR‐497‐5p‐mediated NLRP3/caspase‐1/GSDMD pathway and the resulting inflammatory endothelial dysfunction in ox‐LDL‐stimulated HUVECs was also significantly attenuated after UCP2 overexpression." (PMID 40391195, 2025). "Endothelial dysfunction and impaired angiogenesis stimulated by GSDMD-knockdown macrophage supernatants indicated that intracellular substances and cytokines released by pyroptotic macrophages stimulate endothelial cells and further regulate endothelial function and angiogenesis." (PMID 38906863, 2024).
gram-negative bacterial infections (5 papers, 2021 to 2024). Infections caused by bacteria that show up as pink (negative) when treated by the gram-staining method. "Gram-negative bacterial infection induces cell death that is dependent on CASP11 leading to the cleavage of GSDMD to release its N-terminus and form pores in the plasma membrane." (PMID 34740613, 2021).
hyperlipidemia (5 papers, 2021 to 2024). "Our data confirmed that increased hyperlipidemia-mediated inflammation activated HMGB1-TLR4 signaling, NLRP3 inflammasome formation, and upregulation of pyroptosis markers caspase-1, IL-1β, IL-18, and the pyroptosis executor GSDMD." (PMID 36829889, 2023).
infarction (5 papers, 2022 to 2025). A localised pathological necrosis of tissue resulting from obstruction of the blood supply usually by a thrombus, an embolus, or vascular torsion. "In our study, we emphasize the pivotal role of GSDMD in the acute setting post infarction since the association of GSDMD with microvascular injury remained independent even after adjustment for IL-1β." (PMID 37424923, 2023). "Emodin pretreatment ameliorated GSDMD‐mediated myocardial pyroptosis and reduced infarction in I/R rats." (PMID 39929748, 2025). "Meanwhile, the mean T1 values of infarcted myocardium were higher in patients with high GSDMD concentrations (≧ 13 ng/L) both in the acute and chronic phase after infarction (1564 ± 79 ms vs. 1370 ± 50 ms, P = 0.01; 1660 ± 73 ms vs. 1335 ± 48 ms, P = 0.01)." (PMID 37424923, 2023). "WT and GSDMD KO mice were randomly subjected to I 45 min/R 24 h or sham surgery, and echocardiography, infarction size, and serum LDH were determined." (PMID 35783187, 2022). "Furthermore, patients with high GSDMD concentrations (≧13 ng/L) showed a lower LVEF both in the acute phase after infarction (35% vs. 54%, P < 0.001) and in the chronic phase (42% vs. 56%, P < 0.001)." (PMID 37424923, 2023). "Results showed that AM-SB significantly reduced infarction volume, inflammation (IL-1β, TNF-α), and pyroptosis-related markers (NLRP3, GSDMD, ASC, Caspase-1), while decreasing gliosis and improving cerebral metabolites." (PMID 39859214, 2025). "Our data suggest that increased GSDMD levels in the serum exert negative effects on LVEF and are associated with a larger infarction and left ventricular volume assessed by CMR." (PMID 37424923, 2023).
keratitis (5 papers, 2021 to 2024). A corneal disease that is characterized by inflammation of the cornea. "Pretreatment with GSDMD siRNA via subconjunctival injection alleviated keratitis by suppressing IL-1β levels as well as neutrophil and macrophage recruitment in mice models of A. fumigatus keratitis." (PMID 35655803, 2022). "Our results indicated that multiple proteins that were associated with inflammasome and pyroptosis (NLRP3, ASC, CAP1, GSDMD, IL-1β and IL-18) were highly expressed in C. albicans keratitis." (PMID 35463001, 2022). "In the corneas of rats and patients with keratitis, P. aeruginosa enhanced the levels of caspase-4/5/11, cleaved GSDMD, and proinflammatory cytokine, which was rescued by wedelolactone." (PMID 35655803, 2022). "Based on these findings, GSDMD and caspase-1 are potential novel therapeutic targets for A. fumigatus keratitis." (PMID 35655803, 2022). "The study indicated the involvement of non-canonical pyroptosis in P. aeruginosa keratitis, and the expression of caspase-4/5/11 and cleaved GSDMD in LPS-induced cell models, keratitis rat models, and P. aeruginosa keratitis patients was increased." (PMID 34925047, 2021). "When the NLRP3 inflammasome is activated, a large amount of the proinflammatory cytokines IL-1β and IL-18 are released through GSDMD pores, which may trigger and aggravate corneal inflammation and result in enhanced ocular injury in C. albicans keratitis." (PMID 35463001, 2022). "Another recent study on mouse fungal keratitis demonstrated that inhibiting GSDMD expression with GSDMD siRNA could improve the outcome of keratitis, which was characterized by decreased corneal inflammation, suppressed neutrophil and macrophage infiltration and reduced production of IL-1β." (PMID 35463001, 2022). "Moreover, it was reported that the expression of GSDMD, a pyroptosis executor, was significantly increased in human and mouse A. fumigatus keratitis, as well as in HCECs infected with A. fumigatus, suggesting that corneal epithelial cells are able to respond to fungal infection via pyroptosis." (PMID 35463001, 2022). "Neutrophils have also been shown to play a key role in a murine model of P. aeruginosa corneal infection (keratitis), where neutrophils secrete high levels of IL-1β, which requires the T3SS needle and translocon proteins along with gasdermin D (GSDMD)." (PMID 39062975, 2024). "As there was no role for GSDMD or GSDME in P. aeruginosa keratitis, and as these bacteria induce NETs in murine models of pulmonary and corneal infections, we examined if this is related to NETosis induced by P. aeruginosa." (PMID 37730693, 2023).
lymph node metastasis (5 papers, 2022 to 2025). "In our study, the expression of GSDMD was only related to lymph node metastasis(P < 0.05)." (PMID 37194012, 2023). "The intersection analysis revealed that three factors, GSDMD, CCND1, and BATF2, were upregulated in postchemotherapy OSCC tumor tissues and highly expressed in tumors from patients with neck lymph node metastasis." (PMID 40178046, 2025). "The data of 65 patients with ccRCC in the First Affiliated Hospital of Xinjiang Medical University were analyzed, and the expression of GSDMD was correlated with TNM stage, Fuhrman grade, lymph node metastasis, sex, and smoking (p < 0.05)." (PMID 37483501, 2023). "The expression of GSDMD immunohistochemical protein was correlated with TNM stage, Fuhrman grade, lymph node metastasis, sex, and smoking." (PMID 37483501, 2023). "Increased cleaved gasdermin D expression was associated with a body mass index of >25 kg/m2, FIGO grades 1–2, early FIGO stage (I–II), and absence of lymph node metastasis." (PMID 38562170, 2024). "According to the prognostic information of clinical patients, it was found that GSDMD was significantly correlated with TNM stage, Fuhrman grade, lymph node metastasis, gender, and smoking or not, and the prognosis of patients with high expression of GSDMD was worse." (PMID 37483501, 2023).